TRIM21 (tripartite motif containing 21)
Diseases named in the same sentence as TRIM21 in open-access papers (continued):
Sharing a sentence is not in itself a finding about the gene and the disease.
gastric cancer (13 papers, 2022 to 2025). A primary or metastatic malignant neoplasm involving the stomach. "In addition, TRIM21 was associated with the presence of different immune cells, including NK cells, T cells, and dendritic cells in gastric cancer, as demonstrated by bioinformatics analysis." (PMID 39768197, 2024). "STAT1 (Signal transducer and activator of transcription 1) represses the transcriptional activity of TRIM21 in gastric cancer." (PMID 40936722, 2025). "In conclusion, this study underscored the importance of the miR-99a-3p/TRIM21 axis in the regulation of tumor growth, thus offering potential insights into therapeutic strategies for gastric cancer." (PMID 38720056, 2025). "Collectively, TRIM21 acts as a tumor suppressor in gastric cancer by inhibiting tumor growth, migration, and proliferation while enhancing apoptosis and chemosensitivity through the downregulation of EZH1." (PMID 39768197, 2024). "TRIM21 inhibits the stemness of gastric cancer cells and functions as a sensitizer to apatinib treatment." (PMID 39154024, 2024). "Compared with nearby normal tissues, TRIM21 expression was reduced in gastric cancer, which was mediated by STAT1." (PMID 39768197, 2024). "A study found that apatinib-reduced gastric cancer cell proliferation was significantly abolished by TRIM21 knockdown; in turn, promoting TRIM21 expression further improved the sensitivity of gastric cancer cells to apatinib." (PMID 36261847, 2022). "TRIM21 expression was markedly downregulated in tumor tissues of gastric cancer patients." (PMID 39768197, 2024). "TRIM21 overexpression significantly enhances apoptosis and inhibits stem cell properties in GC cells; moreover, TRIM21 can inhibit EZH1 (an enhancer of zeste homolog 1) stability to improve gastric cancer apatinib therapy." (PMID 40936722, 2025). "This stabilization prevented the ubiquitination and degradation of tripartite motif-containing protein 21(TRIM21)-mediated heterogeneous nuclear nucleoprotein A1 (hnRNPA1) through the PKM2 signaling pathway, thereby supporting the progression of gastric cancer." (PMID 39791162, 2025). "In vitro, the interaction between STAT1 and the TRIM21 promoter was confirmed in 293FT cells, and in vivo, TRIM21 overexpression in MKN45 cells suppressed tumor growth in nude mice, aligning with its tumor-suppressive role in gastric cancer." (PMID 39768197, 2024). "For example, in gastric cancer, through a GTPase manner, TGM2 inhibits tripartite motif-containing protein 21 (TRIM21)-mediated ubiquitination and degradation of signal transducer and activator of transcription 1 (STAT1), and thus enhances its stability and oncogenic actions." (PMID 39115570, 2024). "In gastric cancer, higher TRIM21/Ro52 expression not only is correlated with a lower recurrence and a better 5-year survival rate but also enhances the chemosensitivity of the tumor cells to apatinib, an FDA-proved treatment for chemotherapy-refractory advanced gastric cancer." (PMID 37993883, 2023).
non-small cell lung carcinoma (13 papers, 2020 to 2025). A group of at least three distinct histological types of lung cancer, including non-small cell squamous cell carcinoma, adenocarcinoma, and large cell carcinoma. "To identify the E3 ligase responsible for K48-linked GRP78 ubiquitination, we focused on TRIM21, implicated in GRP78 degradation in non-small cell lung cancer." (PMID 40830980, 2025). "In transformed non-small cell lung cancer cells, F-actin bundling spatially sequesters the E3 ligase TRIM21, thus reducing its substrate PFKP degradation and enhancing glycolysis." (PMID 38351096, 2024). "The E3 ligase TRIM21 promotes K63-linked ubiquitination of GAC, inhibiting its activity in non-small cell lung cancer." (PMID 39048965, 2024). "Lys311 acetylation on GAC strengthens the interaction between GAC and TRIM21, therefore promoting GAC K63-linked ubiquitination mediated by TRIM21 and inhibiting GAC activity in non-small cell lung cancer." (PMID 36159815, 2022). "In summary, the current study provides a novel regulatory mechanism of p62 oligomerization and autophagosome targeting in autophagy induced by IFN-β via TRIM21 ISGylation in human non-small-cell lung carcinoma A549 cells." (PMID 34257278, 2021). "In non-small cell lung cancer, PD-L1 degradation by TRIM21 could improve anti-tumor effects of CD8-positive T cells." (PMID 40998798, 2025). "Furthermore, acetylation of Lys311 on GAC further enhances this inhibitory process, thereby suppressing non-small cell lung cancer progression and offering new insights for targeting TRIM21 in lung cancer therapy." (PMID 39048965, 2024). "However, transformed non-small cell lung cancer cells maintain high levels of glycolysis by downregulating TRIM21 and isolating residual TRIM21 in the substrate-insensitive stress-fiber subset, regardless of the changing environmental mechanics." (PMID 35392171, 2022). "In non-small cell lung cancer (NSCLC), IFN-I drives HERC5-dependent ISGylation of the E3 ligase TRIM21, which enhances its enzymatic activity." (PMID 41193953, 2025). "The E3 ubiquitin ligase TRIM21 mediates ubiquitination and degradation of PFK1 but is downregulated in some cancers, including hepatocellular carcinoma and non-small cell lung cancer (NSCLC)." (PMID 37176148, 2023). "Regardless of the changes in the cellular microenvironment, there is a tendency for TRIM21/Ro52 inactivation to result in higher PFK1 expression and higher glycolysis rates in human non-small-cell-lung-cancer cells." (PMID 37993883, 2023). "The transformed cells of non-small cell lung cancer that, despite the changed environmental conditions, maintain high glycolysis via the increased PFK expression, down-regulate TRIM21 and sequester residual TRIM21 on a subset of stress fibers that are insensitive to substrate stiffness." (PMID 32300553, 2020).
nasopharyngeal carcinoma (12 papers, 2019 to 2025). A carcinoma arising from the nasopharyngeal epithelium. "Here, based on analysis of bulk and single-cell RNA sequencing (scRNA-seq) data, we first show that the expression of the E3 ligase TRIM21 is inversely associated with radiation-induced antitumour immunity in nasopharyngeal carcinoma (NPC)." (PMID 36797289, 2023). "TRIM21 promoted degradation of mitochondrial voltage-dependent anion-selective channel protein 2 (VDAC2) through K48-linked ubiquitination in nasopharyngeal carcinoma, thereby inhibiting type I interferon response after radiotherapy in nasopharyngeal carcinoma." (PMID 39543140, 2024). "For instance, in nasopharyngeal carcinoma, TRIM21-mediated K48-linked ubiquitination promotes the degradation of LHPP and then downregulates TYK2-STAT1phosphorylation to inhibit the progression of nasopharyngeal carcinoma." (PMID 40379610, 2025). "TRIM21 was found to suppress the radiation‐induced dissemination of mitochondrial DNA and compromise the antitumour immune response in nasopharyngeal carcinoma." (PMID 39556022, 2024). "In addition, it was found that FGF-19 enhances angiogenesis in nasopharyngeal carcinoma by preventing tripartite motif containing 21 (TRIM21)-mediated Annexin II degradation, thereby increasing VEGF expression." (PMID 40232500, 2025). "Here, the authors demonstrate that the E3 ubiquitin ligase and intracellular Fc receptor, TRIM21, impairs CD8+ T cell responses in nasopharyngeal carcinoma tumour models following ionizing radiation." (PMID 36797289, 2023). "Here, we demonstrate that the expression of the E3 ubiquitin ligase, tumour cell-intrinsic tripartite motif-containing 21 (TRIM21) in tumours, is inversely associated with the response to radiation and CD8+ T cell-mediated antitumour immunity in nasopharyngeal carcinoma (NPC)." (PMID 36797289, 2023).
Sepsis (12 papers, 2010 to 2026). Sepsis is defined as life-threatening organ dysfunction caused by a dysregulated host response to infection. "Heparin-binding protein (HBP), released during sepsis, obstructs the K48-linked ubiquitination of the E3 ubiquitin ligase TRIM21, thereby stabilizing TRIM21 and facilitating the K63-linked ubiquitination of transcription factor p65." (PMID 40643532, 2025). "In this study, we indicated that OAS3 protein increases in a proteasomal-dependent way and OAS3 K48-linked polyubiquitination decreases due to the E3 ligase TRIM21 downregulation in the sepsis model, which is consistent with the traditional degradative function of K48-linked chains." (PMID 39494334, 2024). "Collectively, these results suggest that in sepsis, the elevation of TRIM21 contributes to increased endothelial permeability by promoting the ubiquitination and degradation of VE‐Cadherin, thereby disrupting vascular homeostasis." (PMID 41532698, 2026). "Previous studies, using TRIM21 knockout mice, reported that the inflammatory response was significantly weakened, and that survival rates were notably improved during LPS‐induced sepsis." (PMID 41532698, 2026). "Compared to wild‐type (WT) controls, TRIM21‐KO mice exhibited significantly increased expression of VE‐Cadherin in blood vessels, along with reduced microvascular permeability in the liver, lungs and kidneys following LPS‐induced sepsis." (PMID 41532698, 2026). "In addition, the deubiquitination of OAS3 due to the downregulation of the E3 ligase TRIM21 promotes epithelial cell apoptosis and drives sepsis-induced acute lung injury." (PMID 40170095, 2025). "For the first time, we identified TRIM21 as the E3 ligase accounting for OAS3 K48-linked polyubiquitination at the K1079 site and its dowregulation in the sepsis model led to a decrease in the OAS3 ubiquitination level and an increase in the OAS3 protein level in lung epithelial cells." (PMID 39494334, 2024). "Notably, overexpression of TRIM21 in MLE12 cells or mice reversed the sepsis-induced increase in OAS3 protein level." (PMID 39494334, 2024). "Very recently, it has been reported that TRIM21 from human lung endothelial cells displays a modulatory role during the inflammatory response to lipopolysaccharide (LPS), suggesting that TRIM21 is a potential therapeutic target in sepsis-induced endothelial dysfunction." (PMID 31540324, 2019). "Third, FTO O-GlcNAcylation promotes TRIM21-mediated FTO ubiquitination degradation, which induces Socs1 m6A methylation and sustains SOCS1 induction to maintain the negative feedback control of macrophage inflammatory cytokine storm in sepsis." (PMID 40642069, 2025). "However, we did not observe that Trim21 promoted ubiquitin-mediated degradation of Stat3 in renal tubular cells during sepsis-induced AKI." (PMID 40344718, 2025). "Morever, it has been revealed that E3 ligase TRIM21 in lung endothelial cells exhibits a modulatory function during the inflammatory response to LPS18,32, indicating that TRIM21 may serve as potential therapeutic target for lung injury during sepsis." (PMID 39494334, 2024).
xerophthalmia (12 papers, 2013 to 2025). "An analysis of polymorphic markers revealed the association of TRIM21 gene and PTPN22 gene polymorphisms with the risk of developing exogenous dry eye." (PMID 40693714, 2025). "Photosensitivity and xerophthalmia/xerostomia were the only features found to be positively associated with both anti-SSA/Ro60 and anti-Ro52/TRIM21." (PMID 24294139, 2013). "In contrast, photosensitivity and xerophthalmia/xerostomia showed a not statistically significant positive association with both anti-SSA/Ro60 and anti-Ro52/TRIM21." (PMID 24294139, 2013).
glioblastoma (11 papers, 2020 to 2025). The most malignant astrocytic tumor (WHO grade IV). "P27KIP1 has been previously reported as a substrate of TRIM21 in cervical cancer HeLa cells and glioblastoma T98G cells." (PMID 39875724, 2025). "For example, on the one hand, TRIM21 translocated β-catenin from cytoplasm to nucleus, thus promoting glioblastoma progression." (PMID 40998798, 2025). "We detected an increase of CHK1 activation, as measured by CHK1 phosphorylation at Ser345, this increase was induced by temozolomide treatment in a TRIM21 knockdown glioblastoma U87 cell line." (PMID 35048968, 2022). "Therefore, TRIM21 is a novel target for glioblastoma treatment." (PMID 33193404, 2020). "In human glioblastoma, blocking of TRIM21/Ro52 activity due to protein kinase B (AKT) activation impairs the proteasomal degradation of phosphofructokinase-1 (PFK1), the rate-limiting glycolysis enzyme, resulting in the promotion of glycolysis and brain tumor proliferation." (PMID 37993883, 2023).
osteosarcoma (11 papers, 2020 to 2024). A usually aggressive malignant bone-forming mesenchymal neoplasm, predominantly affecting adolescents and young adults. "Compared with osteoblast cell lines, osteosarcoma cells exhibit a notable decrease in TRIM21 protein expression." (PMID 38595915, 2024). "We recently demonstrated that Trim21 plays a crucial role in regulating osteoblast (OB) differentiation in osteosarcoma." (PMID 37884520, 2023). "Overexpression of TRIM21 makes osteosarcoma more resistant to various stresses and promotes its proliferation." (PMID 34026613, 2021). "In order to explore whether TRIM21 can act as an E3 ligase for PDGFRβ, we depleted human osteosarcoma cells (U2OS) of TRIM21 using siRNA." (PMID 37175489, 2023). "Trim21 is fundamental for regulating OB differentiation in osteosarcoma, yet its expression and role in skeletal degenerative disorders, including osteoporosis, are largely unknown." (PMID 37884520, 2023). "Furthermore, the Western Blot analyses showed that the protein expression level of TRIM21 was significantly downregulated in osteosarcoma patient specimens, consistent with the overexpression of SGLT2 in osteosarcoma patient specimens." (PMID 35662245, 2022). "Therefore, the overexpression of SGLT2 at the protein level could be attributed to the SGLT2 degradation induced by TRIM21 in osteosarcoma." (PMID 35662245, 2022). "We report here that another E3 ligase, i.e., tripartite motif-containing protein 21 (TRIM21), contributes to the ubiquitination of PDGFRβ in human primary fibroblasts AG1523 and the osteosarcoma cell line U2OS and regulates basal levels of PDGFRβ." (PMID 37175489, 2023). "To further explore the mechanisms responsible for SGLT2 up-regulation in osteosarcoma, we performed LC-MS/MS and found that SGLT2 interacted with TRIM21 (tripartite motif containing 21)." (PMID 35662245, 2022). "In contrast, our study indicated that the overexpression of TRIM21 resulted in an increased degradation of SGLT2, which induced the expression of STING and the activation of the IRF3/IFN-β pathway in osteosarcoma." (PMID 35662245, 2022). "However, whether the expression level of TRIM21 was decreased in osteosarcoma tissues compared with non-osteosarcoma still be unclear, which need further researched." (PMID 35662245, 2022).
colon cancer (10 papers, 2020 to 2025). "To investigate the role of TRIM21 in CRC, we utilized the Clinical Proteomic Tumor Analysis Consortium (CPTAC) database to analyze the protein expression level of TRIM21 in colon cancer patients." (PMID 39890802, 2025). "The findings revealed a significant decrease in TRIM21 expression in colon cancer tissues compared to normal tissues." (PMID 39890802, 2025). "Analyzing RNA sequencing data from TCGA and GTEx databases revealed elevated TRIM21 expression in colon cancer tissues compared to normal tissues." (PMID 39543140, 2024). "In our study, MDM4 is found to upregulate the TRIM21 expression level to inhibit the ubiquitination of GPX4, and promotes colon cancer progression." (PMID 39543140, 2024). "To examine and confirm the relationship among CSN6, TRIM21 and ALDH1A1 in human cancers, we performed IHC staining on a TMA from our human colon cancer cohort to assess the expression of CSN6, TRIM21 and ALDH1A1." (PMID 32225170, 2020).
overlap syndrome (10 papers, 2008 to 2025). "Anti-TRIM21 were the second most common autoantibodies in this SSc.Anti-TRIM21 was strongly associated with ILD (OR=1.53 [1.11-2.12], P=0.0091) and overlap syndrome (OR=2.06 [1.01-4.19], P=0.0059)." (PMID 39165359, 2024). "Notable among the IFN-induced autoantigens is Ro52 (encoded by the TRIM21 gene), which is targeted by autoantibodies in many rheumatic diseases, including pSS, SLE, DM, SSc and overlap syndromes." (PMID 37228405, 2023). "Other autoantibodies, including anti-U1-RNP, anti-PM-Scl, anti-Ku, anti-Ro60/SS-A, anti-Ro52/TRIM21, and anti-NOR 90 tend to be found in SSc-overlap syndromes as well as in other ARD, and are considered less specific for SSc." (PMID 25926833, 2015).
pulmonary fibrosis (10 papers, 2012 to 2025). Chronic progressive interstitial lung disorder characterized by the replacement of the lung tissue by connective tissue, leading to progressive dyspnea, respiratory failure, or right heart failure. "Based on the cluster analysis, we believe anti-VEGFB antibodies and anti-TRIM21/Ro52 antibodies should be further investigated in the context of digital ulcers and lung fibrosis and/or PAH in SSc patients." (PMID 36982700, 2023). "On the other hand, cluster 2 is mostly driven by anti-TRIM21/Ro52 antibodies and showed the highest frequency of patients with lung fibrosis and PAH." (PMID 36982700, 2023). "TRIM21 expression in idiopathic pulmonary fibrosis lung fibroblasts is regulated by pirfenidone, and Ro52/TRIM21 activity might be correlated with lung fibrosis in patients with idiopathic pulmonary fibrosis." (PMID 37007784, 2023). "Further studies are required to support the hypothesis of increased risk of lung fibrosis and PPF in anti-Ro52 positive patients with idiopathic inflammatory myopathies myositis-ILD, and to elucidate the possible role of Ro52/TRIM21 in the pathogenesis of lung fibrosis." (PMID 37007784, 2023). "Ro52/TRIM21 is a E3-ubiquitin ligase owing to the TRIM superfamily and several members of this superfamily are involved in fibrosing processes, including lung fibrosis." (PMID 37007784, 2023).
liver cancer (9 papers, 2020 to 2025). An epithelial or non-epithelial malignant neoplasm that arises from the liver. "The elevated TRIM21 and TRIM25 levels in liver cancer patients and the increased hazard ratio in patient groups with high TRIM21 and TRIM25 expression indicates the association of these TRIM proteins and vtRNA1-1 levels with tumor progression." (PMID 40096176, 2025). "TRIM21 regulates SREBF1 protein stability through ubiquitination to weaken kidney cancer onset, and in liver cancer, TRIM21 enhances progression via inhibiting p62-Keap1-Nrf2 pathway." (PMID 41249119, 2025). "Thus, targeting EPDR1 and TRIM21 holds promise as a novel strategy for improving liver cancer immunotherapy." (PMID 39152265, 2024). "TRIM21 promotes liver cancer by inhibiting the p62-Keap1-Nrf2 antioxidant pathway." (PMID 37171396, 2023). "In contrast to liver cancer cells, TRIM21 knockdown did not affect vtRNA1-1 levels in HeLa cells, suggesting that the effect of TRIM21 depletion on vtRNA1-1 might be cancer-type dependent." (PMID 40096176, 2025).